ETF1 (eukaryotic translation termination factor 1)
Description:
Component of the eRF1-eRF3-GTP ternary complex, a ternary complex that mediates translation termination in response to the termination codons. The eRF1-eRF3-GTP complex binds to a stop codon in the ribosomal A-site. ETF1/ERF1 is responsible for stop codon recognition and inducing hydrolysis of peptidyl-tRNA. Following GTP hydrolysis, eRF3 (GSPT1/ERF3A or GSPT2/ERF3B) dissociates, permitting ETF1/eRF1 to accommodate fully in the A-site and mediate hydrolysis of peptidyl-tRNA. Component of the transient SURF complex which recruits UPF1 to stalled ribosomes in the context of nonsense-mediated decay (NMD) of mRNAs containing premature stop codons. Required for SHFL-mediated translation termination which inhibits programmed ribosomal frameshifting (-1PRF) of mRNA from viruses and cellular genes.
Synonyms: eRF1; RF1; SUP45L1; TB3-1; D5S1995; ERF
Tractability: Small molecule: a structure with a bound ligand is known. PROTAC: UniProt records ubiquitination sites on it; ubiquitination databases record sites on it; its protein half-life has been measured.
Gene: Protein-coding gene on chromosome 5 (138,506,093 to 138,543,239, reverse strand). Ensembl gene ENSG00000120705.
Subcellular location: Cytoplasm
Pathways (Reactome):
Metabolism of RNA: Nonsense Mediated Decay (NMD) enhanced by the Exon Junction Complex (EJC); Nonsense Mediated Decay (NMD) independent of the Exon Junction Complex (EJC)
Metabolism of proteins: Eukaryotic Translation Termination; Protein hydroxylation
Developmental Biology: Regulation of expression of SLITs and ROBOs
Gene Ontology:
Molecular function: peptidyl-tRNA hydrolase activity; protein binding; RNA binding; sequence-specific mRNA binding; translation release factor activity; translation termination factor activity; ribosome binding; translation release factor activity, codon specific
Biological process: protein methylation; regulation of translational termination; translational termination; cytoplasmic translational termination
Cellular component: cytoplasm; cytosolic ribosome; nucleus; translation release factor complex; cytosol
Genetic constraint (gnomAD): Loss-of-function variants: 4 observed, 48.23 expected, observed/expected ratio (o/e) 0.0829, 90% interval 0.04 to 0.19. The upper end of that interval is the gene's LOEUF score, 0.19, which puts it in group 1 of 6, group 1 being the genes least tolerant of losing a copy. Missense variants: 125 observed, 471.54 expected, observed/expected ratio (o/e) 0.27, 90% interval 0.23 to 0.31. Synonymous variants: 136 observed, 165.53 expected, observed/expected ratio (o/e) 0.82, 90% interval 0.71 to 0.95.
Homologues: Orthologues: dog ETF1 (100% identical), guinea pig ETF1 (100% identical), macaque ETF1 (100% identical), mouse Etf1 (100% identical), pig ETF1 (100% identical), rabbit ETF1 (100% identical), rat Etf1 (100% identical), tropical clawed frog etf1 (99% identical), zebrafish etf1b (97% identical), chimpanzee ETF1 (94% identical), zebrafish etf1a (83% identical), Drosophila melanogaster eRF1 (82% identical), and 1 more.
Diseases named in the same sentence as ETF1 in open-access papers:
ETF1 is named in the same sentence as 22 diseases in open-access papers, as found by Europe PMC text mining. Sharing a sentence is not in itself a finding about the gene and the disease. The quoted sentences say what the papers report.
breast carcinoma (2 papers, 2020 to 2025). "Further verification found that ETF1 could be involved in the development of breast cancer and might serve as a biomarker of the HER2 subtype group." (PMID 32469390, 2020).
COVID-19 (1 paper, 2025). A disease caused by infection with severe acute respiratory syndrome coronavirus 2. "Our analysis of the cis-eQTL effects of the SNP rs1042665 HSPA9 suggests a complex interplay of gene regulation involving KDM3B, ETF1, FAM53C, KLHL3, and DNAJC18, potentially contributing to COVID-19 severity." (PMID 41009536, 2025).
prostate carcinoma (1 paper, 2019). A carcinoma that arises from epithelial cells of the prostate gland. "Second, independently of ETF1 methylation, N6AMT1 monomethylates H4K12 and controls the proliferation of prostate cancer cells through the expression of genes involved in the cell cycle." (PMID 31466382, 2019).
tick-born disease (1 paper, 2023). "In addition to providing a potential treatment of the tick-born disease, the macrocyclic peptidyl Etf-1 inhibitors have served as useful chemical probes to gain significant insight into the molecular mechanism of E. chaffeensis infection." (PMID 36874272, 2023).
cancer (5 papers, 2018 to 2025). A tumor composed of atypical neoplastic, often pleomorphic cells that invade other tissues. "Activation of ETF1 could effectively increase cancer cell invasion and metastasis, which may provide new insights for developing therapeutic strategies." (PMID 35720008, 2022).
infection (3 papers, 2017 to 2023). The state of being infected such as from the introduction of a foreign agent such as serum, vaccine, antigenic substance or organism. "Initial screening of a macrocyclic peptide library identified peptides B7 and C8 as moderately potent Etf-1 binders (low μM KD) that are cell permeable and inhibit host cell infection by E. chaffeensis." (PMID 36874272, 2023). "As infection progresses, Etf-1 is diverted to autophagosomes as mitochondria begin to lose membrane potential." (PMID 35155275, 2021). "This suggests that host-cell physiologic conditions during infection influence the distribution of Etf-1 between mitochondria and autophagosomes, consequently affecting E. chaffeensis growth." (PMID 35155275, 2021). "The majority of Etf-1 targets mitochondria during the early stage of infection when mitochondrial membrane potential is maximal." (PMID 35155275, 2021). "Etf-1-GFP-transfection of HEK293 cells enhanced infection by Etf-1 PNA-treated E. chaffeensis compared to the GFP-transfection CTL as well." (PMID 28638803, 2017). "As we previously reported with non-PNA-treated E. chaffeensis, based on the levels of E. chaffeensis 16S rRNA/human GAPDH mRNA, Etf-1-GFP-transfection of HEK293 cells enhanced infection of CTL PNA-treated E. chaffeensis compared to the GFP-transfection CTL." (PMID 28638803, 2017). "Etf-1 is also imported by host cell mitochondria where it inhibits host cell apoptosis to prolong its infection." (PMID 28638803, 2017). "Since the obligatory intracellular bacterium E. chaffeensis requires a secreted effector protein Etf-1 for host cell infection, inhibitors against the Etf-1 protein may provide effective treatments of E. chaffeensis infections." (PMID 36874272, 2023). "Etf-1 is highly produced and secreted by E. chaffeensis in human monocytes; neutralization of secreted Etf-1 by delivering anti-Etf-1 IgG into the cytoplasm of host cells inhibited cellular infection by E. chaffeensis, whereas ectopic Etf-1 expression enhanced E. chaffeensis infection." (PMID 28638803, 2017). "Knowing that the PNA was specific for its target gene, we evaluated ability of Etf-1 PNA to suppress Etf-1 mRNA expression in ehrlichiae and inhibit its infection of human monocytes." (PMID 28638803, 2017). "When E. chaffeensis was treated with PNA specific to Etf-1, host cell autophagy induction and E. chaffeensis infection were significantly reduced, which validated the critical role of the T4SS effector for autophagy induction and E. chaffeensis infection." (PMID 28638803, 2017). "The result indicated that Etf-1 mRNA and protein expression was effectively knocked down with the Etf-1 PNA, Etf-1 was required for E. chaffeensis infection, and thus, the PNA approach was useful for examining the requirement of target ehrlichial genes in infection." (PMID 28638803, 2017).
tumor (3 papers, 2017 to 2021). "We verified the expression of ADARB1, ETF1, NRP1, and VPS26A in GBM tumor tissues and normal brain tissues through GEPIA." (PMID 32469390, 2020). "Among them, ADARB1 had a lower expression in tumor tissues (P<0.05), and ETF1 and NRP1 were highly expressed in tumor tissues (P<0.05)." (PMID 32469390, 2020). "In the HPA data, compared with normal tissues, the expression of PKMYT1, ETF1, RECQL4, TUBB2B, and CDC6 in tumor tissues was remarkably upregulated, while the expression of TFRC and PITX1 was significantly downregulated (,ECT2, BUBB1B, and COCH were not included)." (PMID 33869220, 2021). "According to the CPTAC data, the protein expression of PKMYT1, ETF1, ECT2, BUB1B, and RECQL4 in tumor tissues was significantly increased, while the expression of TFRC was significantly reduced, and the expression of COCH and TUBB2B did not change significantly (PITX1 and CDC6 were not included)." (PMID 33869220, 2021). "Other up regulated cellular proteins which were identified included the cytoskeletal-related actin binding protein Twinfilin-1 (TWF1) (Rsc 5.1), and the tumor suppression-related proteins Apolipoprotein A-1 (APOA1) (Rsc 5.1) and Eukaryotic release factor 1 (ETF1) (Rsc 2.3)." (PMID 28406185, 2017).
psychiatric disorder (2 papers, 2016 to 2025). A disorder characterized by behavioral and/or psychological abnormalities, often accompanied by physical symptoms. "We considered that the associations of ETF1 gene are more specific to BP-II but not with other psychiatric disorders, which benefit from more homogeneous phenotypic presentations in our samples." (PMID 27450446, 2016).
ETF1 also shares sentences with these, for which no sentence is quoted: schizophrenia (3 papers); depression (2); diabetes (2); developmental delay (1); epilepsy (1); hemophilia (1); Insulin resistance (1); lung carcinoma (1); myeloid tumors (1); Nephropathy (1); Obesity (1); oral cancer (1); Parkinson’s (1); renal cell carcinoma (1).